CTLA4 (cytotoxic T-lymphocyte associated protein 4)
Diseases named in the same sentence as CTLA4 in open-access papers (continued):
Sharing a sentence is not in itself a finding about the gene and the disease.
tumor (continued). "Hence, the tumor cells with high CTLA-4 mRNA expression may be resistant to Everolimus." (PMID 32602545, 2020). "Both anti-CTLA4 and anti-PD-1 antibodies induce IDO and the combination of ICIs with 1-methyl-D-tryptophan, an inhibitor of IDO, is able to suppress tumor growth of HCC in a mouse model." (PMID 32443599, 2020). "T-cell exhaustion (CD8+ PD-1+/CTLA-4+) and treatment-induced depletion of regulatory T-cells (CD4+ Foxp3+/CTLA-4+) was seen in tumor or blood in 5/5 patients with clinical benefit, but only in one non-responder." (PMID 32681091, 2020). "Combination with anti–CTLA-4 led to tumor regression accompanied by enhanced T cell activity, increase in activated CD86+ monocytes in the tumor, augmentation of pro-inflammatory IFNγ, TNFα, and IL-6 and decrease in immunosuppressive MCP-1 and IL-10 cytokines." (PMID 32793228, 2020). "Collectively, we found that PD-1, CTLA-4, VISTA, CD28, OX-40, 4-1BB, ICOS, and GITR were significantly increased in tumor tissues compared with non-tumor tissues." (PMID 33552954, 2020). "By targeting CTLA-4 and OX40 simultaneously, ATOR-1015 is directed to the tumour area where it induces enhanced immune activation, and thus has the potential to be a next generation CTLA-4 targeting therapy with improved clinical efficacy and reduced toxicity." (PMID 32680511, 2020). "One such example, is the bispecific antibody combination targeting OX40 and CTLA-4, which significantly enhanced CD8+ T cells and reduced Tregs specifically within the TME, leading to better tumor control than either therapy alone." (PMID 32849557, 2020). "In order to study the efficacy of new combinatorial treatments involving anti-CTLA-4 and anti-EGFR drugs, we decided to test ipilimumab on a panel of tumor cells with other anti-EGFR specific compounds, such as aptamers." (PMID 32024070, 2020). "We found that TOX and potentially TIM-3, CTLA-4, VISTA, TIGIT, KLRG1, TOX2, SIRT1, Ki-67, and Helios mRNA levels in tumor tissue were elevated in advanced disease stages, suggesting their potential roles in CRC progression." (PMID 32393998, 2020). "Combining the antibodies anti-CTLA-4 and anti-4-1BB revealed CD8+ immune responses against advanced MC38 tumours as well as establishment of memory T cells." (PMID 30678059, 2019). "Instead, addition of a combined innate and adaptive immunotherapeutic approach with RT and combined IT-IC, anti-CTLA-4, CpG and anti-CD40 was effective against this cold 9464D-GD2 tumor, with some mice achieving complete tumor regression." (PMID 31810498, 2019). "The anti-tumor responses of ATOR-1015 were studied in a novel hOX40tg mouse model, enabling studies of both OX40- and CTLA-4-mediated effects." (PMID 30975201, 2019). "Given the number of clinical trials investigating anti-PD-1, PDL-1, and CTLA4 antibodies, it is essential to understand how these interventions affect ILC function within the tumor tissue." (PMID 31212601, 2019). "Recently other immune checkpoint inhibitors (e.g., anti-CTLA-4 antibodies, anti-NKG2A antibodies) have been reported to restore cytolytic functions of NK cells and thereby enhance their anti-tumor activity." (PMID 30967859, 2019). "Most importantly, these include expression and release of CTLA-4 by tumor cells per se, as well as release of microvesicle-packaged CTLA-4 by mature myeloid DCs in the tumor microenvironment." (PMID 31616428, 2019). "Similar to human basal-like BC, BBN-induced murine tumors displayed an upregulated expression of immunoinhibitory molecules such as CTLA-4, PD-L1, and IDO1 which can lead to cytotoxic resistance and tumor escape." (PMID 31779626, 2019). "Although ICIs have had a major impact on the therapy of many tumor types and subsequent patients’ lives, the observation of primary and acquired resistance to anti-PD1/PD-L1 and anti-CTLA4 agents leave much room for improvement." (PMID 35582715, 2019).
tumor (continued). "Using 770 immune-related genes, we profiled immune cells infiltrating the tumor following treatment with systemic or IT anti-PD-1, and compared it with another FDA-approved immunotherapy, CTLA-4 blockade." (PMID 31804466, 2019). "Up-regulation of immune checkpoint molecules (PD-1, PD-L1, CTLA-4, TIM-3, Lag-3, TIGIT, CD73, VISTA, B7-H3) in the tumor microenvironment is an important mechanism that restrains effector T cells from the anti-tumor activity." (PMID 30863404, 2019). "In a preclinical study using mouse model, it was shown that check point inhibitors like CTLA-4 and PD-1 activate CD103+ DCs and increase IL-12 secretion by them, leading to an increase in the anti-tumor immune response." (PMID 31164886, 2019). "In only one tumour high expression levels of CD2, CD3, CD4, CD8 CTLA-4 and PD-1 were found, suggesting an inflammatory phenotype (not shown)." (PMID 31747973, 2019). "To identify the immune cell subsets contributing to the outcome of the combination of α-PD-1 with other immune checkpoint antibodies (α-CTLA-4 or α-Lag3), we analyzed the TIL by flow cytometry at day 15 after tumor implantation." (PMID 31533840, 2019). "The combination of PD-1 inhibition and CTLA-4 blockade or of peptide vaccinations and TCR T cell therapy has been reported in clinical trials, showing abilities to suppress tumor development in EC patients." (PMID 31771653, 2019). "Here, when compared with mice treated with PBS, mice on anti-CTLA-4 + PBMC treatment and BsAb-5 + PBMC treatment showed significantly reduced tumor volume." (PMID 29187584, 2019). "Homozygous tumor-bearing hOX40tg mice were treated days 10, 13 and 17 with vehicle, ATOR-1015 or the surrogate anti-CTLA-4 antibodies 9D9 (mouse IgG2a) or 9H10 (hamster IgG), the latter being a more effective Treg depleter." (PMID 30975201, 2019). "A combination of P/a-CTLA-4+P/a-PD-1 further improved survival (by 40% median) in GL261 tumor-bearing mice compared to PBS (p < 0.0001), a-CTLA-4 (p < 0.0001), a-PD-1 (p < 0.0001), P/a-CTLA-4 (p < 0.0001), and P/a-PD-1 (p < 0.004)." (PMID 31462642, 2019). "Anti-CD40/CpG activate innate immunity, mainly macrophages, while anti-CTLA-4 releases the brakes on effector T cells and can deplete CD4+ Tregs in the tumor microenvironment." (PMID 31810498, 2019). "Immunostaining for PD-L1, CTLA-4 and MMR proteins was independently assessed both in immune cells (ICs) and tumor cells (TCs) of primary tumors and metastases, and characterization of IC populations was pursued." (PMID 31614500, 2019). "Expression of cytotoxic T-cell marker CTLA4 varied widely between patients, whereas expression of PD-1 (PDCD1) was uniformly low and tumor cell marker PD-L1 (CD274) was only moderately expressed." (PMID 30881919, 2019). "Pre-clinical data also showed that blockade of CD96 alone or in combination with anti-PD-1 or anti-CTLA-4 or doxorubicin promotes NK cell activity (in terms of IFN-γ release) and a better control of tumor progression." (PMID 31214193, 2019). "On the other hand, CTLA-4 blockades also inhibit the B7-CTLA-4 pathway, which can initiate CD8+ T cell proliferation in lymph nodes and increase the infiltration of CTLs into tumor tissues." (PMID 31014381, 2019). "In this study, we showed that lysates of L. acidophilus combined with anti-CTLA-4 antibody blockade enhanced antitumor immunity in mouse CRC models induced by AOM/DSS, by synergistically improving anti-tumor T cell immunity." (PMID 31882868, 2019). "All three vaccine formulations, SLA–OVA (adm), SLA–OVA (enc) and MS–OVA (enc) in combination with the checkpoint inhibitors anti-PD-1 and anti-CTLA-4 induced OVA-CD8+ T cells detectable in the spleen and tumor." (PMID 31771150, 2019). "In MC38 tumor-bearing SPF mice, response to anti-PD-1 or anti-CTLA-4 antibodies was significantly enhanced in animal colonized with the 11 strains." (PMID 31533218, 2019).
tumor (continued). "Tumor-bearing mice receiving CTLA-4 blockade and pharmacologic or Ab-mediated inhibition of CD73 display superior tumor control and overall survival than counterparts receiving single agent treatments." (PMID 31244820, 2019). "It has been shown that tumor-intrinsic active β-catenin signaling results in decreased CCL4 production, which further induces T-cell exclusion and resistance to anti-PD-L1/anti-CTLA-4 monoclonal antibody therapy." (PMID 31221150, 2019). "Following the accomplishments of PD-1 and CTLA-4 blockade, TIM-3 and LAG-3 are currently being explored in various pre-clinical and clinical trials to promote effective anti-tumor immunity for clinical benefits." (PMID 31921188, 2019). "Therefore, the observed optimal timing of CTLA-4 blocking agents several days before irradiation stems from their enhancement of T-cell induction in the lymph nodes, while PD-1 axis blockade works best when given concomitantly due to the fact of its action directly in the tumor microenvironment." (PMID 31905723, 2019). "The OS tumours OS04 and OS03, and BZ28 and BZ35 that had the highest CD8A gene expression, also had high expression of PD-1, Tim-3, LAG-3 and CTLA4, indicative of a complex dysfunctional state of the CD8 + TILs in these tumours." (PMID 30674975, 2019). "In fact, dietary supplements with Bacteroides fragilis induced Th1 immune responses in the tumor-draining lymph nodes prompted the maturation of DCs in the TME and facilitated the restoration of the clinical response to CTLA-4 blockade." (PMID 32010123, 2019). "By targeting CTLA-4 and OX40 simultaneously, ATOR-1015 is directed to the tumor area where it induces enhanced immune activation, and thus has the potential to be a next generation CTLA-4 targeting therapy with improved clinical efficacy and reduced toxicity." (PMID 30975201, 2019). "In pre-clinical studies, the depletion of Tregs with anti-CTLA-4, anti-CD25 or CCR5 inhibitor r reduced tumor growth and prolonged the animals’ survival by enhancing the activation of tumor specific T cells." (PMID 30987642, 2019). "Here we describe targeted nanoscale immunoconjugates (NICs) on natural biopolymer scaffold, poly(β-L-malic acid), with covalently attached a-CTLA-4 or a-PD-1 for systemic delivery across the BBB and activation of local brain anti-tumor immune response." (PMID 31462642, 2019). "We observed a complete protection from tumor challenge with the anti PD1 and in four out of five animals treated with the anti CTLA-4 antibody which is in line with the protection degree of the NCV delivered by DNA-EP for adjuvant personalized treatment." (PMID 30764846, 2019). "For example, analyzing tumors from patients that did not respond to ipilimumab (anti-CTLA4), various mutations along the interferon-gamma pathway genes (including interferon gamma receptor 1 and 2) were discovered to play a role in promoting tumor cell escape from T cells." (PMID 31067680, 2019). "Preclinical studies showed that CD96 blocking combined with anti-PD1 or anti-CTLA-4 enhances NK cell infiltration and IFN-γ production, thus reducing tumor lung metastases." (PMID 32038612, 2019). "Elevated expression levels of CTLA-4 are often observed in advanced tumor tissues, and blockade of CTLA-4 function frequently reactivates anti-tumor immunity." (PMID 31061392, 2019). "These in vivo data demonstrate a potential additive effect between BET Bromodomain and anti-CTLA-4, correlated primarily with an increased CD8:Treg ratio in the tumor." (PMID 31653272, 2019). "T-regs typically express high levels of CTLA-4, and the anti-CTLA4 checkpoint inhibitor ipilimumab, being an IgG1-class antibody, can mediate Fc-dependent depletion of these cells in the tumor micro-environment (TME)." (PMID 30723469, 2019). "As an example, mAbs that target CTLA4 and PD1 or its ligands, PD-L1/2, have become potent weapons in the armamentarium against cancer by removing an impediment to sustained anti-tumor T cell activity." (PMID 30735510, 2019).
tumor (continued). "The co-administration of the CTLA-4 antibody and human DC vaccines co-transfected with IDO siRNA, the tumor antigen survivin, and human telomerase reversed transcriptase (hTERT) enhanced anti-tumor immunity in a patient with metastatic melanoma." (PMID 30658461, 2019). "A bispecific antibody to CTLA-4 and OX40 has also been effective in pre-clinical models, reducing tumor growth and enhancing response to PD-1 targeted therapy, and is now in phase I clinical trials [NCT03782467]." (PMID 31877721, 2019). "An ongoing immune response can be represented by the upregulation of immune checkpoints (CTLA4, PD-1/PD-L1, IDO and members of the CD33-like siglecs i.e., siglec-7 and siglec-9, but their expression on tumor cells can also be driven by oncogenic pathways." (PMID 31430935, 2019). "Cell line screening showed the enrichment of cancer cells deprived of the expression of CD27, CEACAM1, CTLA4, LRIG1, PDCD1LG2, or TNFRSF18, suggesting their role as tumor suppressor." (PMID 31358815, 2019). "We found increased expression of PD-1 and Tim-3 in all OS tumours and increased expression of LAG-3 in the majority of tumours, whereas CTLA4 had increased expression in fewer tumours." (PMID 30674975, 2019). "Once CTLA-4 binds to its ligand (CD80 and CD86), it impairs T cell function and thus contributes to tumor progression." (PMID 31779642, 2019). "Both CTLA-4 and OX40 are highly up-regulated on tumor-infiltrating Tregs in several types of cancer." (PMID 30975201, 2019). "Further immune characterization revealed that over 50% of tumor infiltrating CD8+ T cells expressed PD-1 and over 10% of splenic CD8+ T cells expressed CTLA-4." (PMID 31409394, 2019). "In EC, Tregs can be recruited by tumor- or stroma-derived chemokines, such as C–C motif ligand 20 (CCL20), and activated by B7/CTLA-4 signaling." (PMID 31771653, 2019). "Tumors with high T-cell signatures from our clustering analysis are concordant with high expression of PD-L1, PD-L2, PD-1, CD80, CD86, CTLA-4, Tim-3, LAG3, 4-1BB, CD8, and CD4, EBV-positive status, and low tumor purity and high immune score." (PMID 30911684, 2019). "Additionally, CTLA-4 antagonists may impede tumor inhibition capabilities of Treg cells." (PMID 31014381, 2019). "Depending on the tumour model used, added beneficial effects were observed when these tumours were concurrently treated with either anti-PD-1, anti-CD137 or anti-CTLA-4." (PMID 31091774, 2019). "We used human CTLA-4 gene knock in mice to show that tumor rejection mediated by Ipilimumab, an FDA-approved anti-CTLA-4 antibody, can be abrogated by an antibody that blocks interaction between IgG Fc and FcgRII and III." (PMID 31681327, 2019). "We found that MIR155HG was significantly associated with immunological checkpoint blocking molecules PD‐1, PD‐L1, CTLA4, LAG3, and TIM3 in many tumors, and some of those types of tumor have better reactivity against immunological checkpoint blockade." (PMID 31568700, 2019). "Our lab previously demonstrated the activity of anti-CTLA-4 in the Myc-Cap model and showed that CTLA-4 immunotherapy significantly increased the production IFN-γ by CD8 and CD4 tumor-infiltrating T cells." (PMID 31653272, 2019). "Kinetic studies revealed that the percentage of Nrp-1+ CD8+ TIL increased during tumour growth, with similar induction of PD-1, LAG-3 and Tim-3 and, to a lesser extent, CTLA-4." (PMID 31350404, 2019). "Ipilimumab, which binds to CTLA-4, was the first CPI to be licensed in 2011, and was initially used for the treatment of metastatic melanoma but is now indicated in multiple tumor types." (PMID 31877721, 2019). "CTLA-4, as a B7/CD28 family member, is involved in tumor immune evasion via down-regulation of CD4+ effector cells (Teff) and promotion of Treg cell activity." (PMID 31824865, 2019).
tumor (continued). "In line with the immunomodulatory role of the tumor microenvironment, CD8+ and CD4+ TILs expressed high levels of inhibitory receptors 2B4, CTLA-4, and PD-1, with the highest levels found on CD103+ TILs." (PMID 30505306, 2018). "In the present study, expression levels of CTLA-4 and PD-L1 were up-regulated in BRAF-IR group with tumor infiltrating immune cells." (PMID 30563160, 2018). "Flowcytometry analysis revealed that the combination treatment recovered the exhausted tumor infiltration lymphocytes (TILs) via inhibiting the expressions of immune checkpoints (PD-1 and Tim-3), while PTX alone evidently increased that of CTLA-4." (PMID 30619178, 2018). "We have characterised further the key contributions of tumour-infiltrating TILs, T effector (CD4+, CD8+), T regulatory (FOXP3+, CTLA-4+) and CD56+ NK cells to pCRs in ALN metastases." (PMID 29390966, 2018). "Similar to CTLA-4, the co-stimulatory receptors GITR, ICOS, and OX40 were consistently expressed on tumor-infiltrating Treg cells in mouse and human tumors." (PMID 29576375, 2018). "Like CD28, CTLA4 is able to bind to CD80 and CD86, which are expressed on the surface of tumor cells and APCs." (PMID 30558227, 2018). "Finally, we reasoned that since antibody treatment is initiated after T cell priming has already taken place in the lymphoid environment, it is possible that anti-CTLA-4 antibodies may promote tumor rejection even if their effect in de novo T cell priming is abrogated." (PMID 29713453, 2018). "Blood and tumour-infiltrating Tregs (FOXP3+, CTLA-4+, PD-1+) play a crucial role in controlling the anti-cancer cellular immune responses in the circulation and tumour microenvironment." (PMID 29390966, 2018). "Induced by RT, VEGF-A can also increase inhibitory receptors on CD8+ T cells (e.g., Tim-3, CTLA-4, PD-1, Lag-3) as well as PDL-1 expression on tumor cells and MDSCs, thereby promoting T cell exhaustion and inactivity." (PMID 30766539, 2018). "Our research group is designing CTLA4-specific CAR-T cells to study the effects of improving immunosuppressive microenvironment and enhancing anti-tumor cytotoxicity." (PMID 29568411, 2018). "The expression of genes related with tumor microenvironment (CD8A, GZMA, and PRF1) can also affect anti-CTLA-4 and anti-PD-1/PD-L1 therapy." (PMID 32793247, 2018). "Anti-CTLA-4 agents can indeed upregulate PD-L1 expression, potentially enhancing theaction of a subsequent PD1/PD-L1 inhibition in tumor microenvironment." (PMID 29552325, 2018). "Venus+ CD4+ T-cells were detected in the tumor, but to a lesser extent than CD8+ T-cells; more venus+ CD4+ T-cells were detected in the tumors of mice treated with anti-PD-1 or anti-CTLA-4 mAb than in the other groups." (PMID 29348598, 2018). "Plasmids were designed to express an optimized anti-CTLA-4 mAb (p(aCTLA-4)) or anti-PD-1 mAb (p(aPD-1)), and were evaluated in a subcutaneous MC38 mouse tumor model." (PMID 30400822, 2018). "The trend of tumor control in mice was similar to that demonstrated with SS1P and anti-CTLA-4 and translated to a significant survival benefit (p < 0.05)." (PMID 30441807, 2018). "The role of TILs, T effector (CD8+, CD4+) and T regulatory (FOXP3+, CTLA-4+, PD-1+) cells and CD56+ NK cells in ALNs is even less well studied and their contribution to the induction of immune-mediated tumour cell death in ALN metastases poorly documented." (PMID 29390966, 2018). "Our lab previously showed tumor-intrinsic WNT/β-catenin activation can mediate T cell exclusion from tumor and primary resistance to anti-CTLA-4 + ant-PD-L1 therapy." (PMID 30400822, 2018). "We found that T-bet was upregulated in tumor-infiltrating CD3+CD8+ T cells upon CQ treatment, whereas the expression of PD1/CTLA-4 was downregulated in CD3+CD8+T-bet+ T cells, consistent with previous report that T-bet represses PD-1 expression." (PMID 29491374, 2018).